UBA6-DT (UBA6 divergent transcript)
Synonyms: LOC550112; UBA6-AS1
Gene: Long non-coding RNA gene on chromosome 4 (67,700,955 to 68,080,952, forward strand). Ensembl gene ENSG00000248049.
Gene Ontology:
Biological process: RNA processing
Cellular component: nucleolus